MECOM (MDS1 and EVI1 complex locus)
Diseases named in the same sentence as MECOM in open-access papers (continued):
Sharing a sentence is not in itself a finding about the gene and the disease.
acute pancreatitis (2 papers, 2020 to 2021). An acute inflammatory process that leads to necrosis of the pancreatic parenchyma. "Altogether, these results indicate that MECOM-deficiency in pancreatic acinar cells under the experimental stress of acute pancreatitis leads to increased acinar cell death with ensuing immune cell infiltration and edema." (PMID 33762742, 2021). "Since the primary cell culture models above recapitulate acinar cell dedifferentiation as it occurs during pancreatitis, we subjected to control and MECOM KO mice to caerulein-induced acute pancreatitis." (PMID 33762742, 2021).
diabetes (2 papers, 2013 to 2024). "This suggests that cuproptosis-related genes may influence the development of diabetes-associated heart failure by altering the structure of functional proteins in cardiomyocytes via MECOM, and these effects may be transmitted epigenetically." (PMID 38883603, 2024).
gastric cancer (2 papers, 2023 to 2025). A primary or metastatic malignant neoplasm involving the stomach. "SPINK 1 upregulation has also been associated with the MECOM-SPINK 1-EGFR-signalling axis in gastric cancer, demonstrating its ability to interact with receptor tyrosine kinases and promote tumor progression." (PMID 40872585, 2025). "Additionally, the MECOM-SPINK 1-EGFR-signalling axis has been identified in gastric cancer, further highlighting the relevance of SPINK 1 in aggressive tumor phenotypes." (PMID 40872585, 2025). "Esophageal cancer patients with high expression of FOXN1, GRHL3, and HES2, stomach cancer patients with high expression of ONECUT2, thyroid cancer patients with high expression of PAX8, and uterine cancer patients that expressed elevated levels of MECOM had decreased survival." (PMID 37627195, 2023).
gynecologic cancers (2 papers, 2021 to 2025). "A comprehensive search of peer-reviewed articles was undertaken to summarize evidence on the role of MECOM in gynecologic cancers." (PMID 41340866, 2025). "This gene module correlates with PAX8 and MECOM expression in large scale profiling of cell lines, patient-derived xenografts (PDXs) and clinical cases and stratifies gynecological cancer cases with worse prognosis." (PMID 33903593, 2021).
kidney cancer (2 papers, 2019 to 2022). Primary or metastatic malignant neoplasm involving the kidney. "Notably, for SETD2 and MECOM, mRNA levels were more than threefold and sixfold lower in kidney cancer cell lines, respectively." (PMID 30755832, 2019). "Recently, it was shown that MECOM interacts with PAX8, a transcription factor that is an oncogene for ovarian and kidney cancers and can serve as an indicator of PAX8 transcriptional activity." (PMID 35581546, 2022).
lung squamous cell carcinoma (2 papers, 2022 to 2025). "Further, MECOM has been associated with aggressiveness of intrahepatic cholangiocarcinoma and also functions as prognostic biomarker in glioblastoma multiforme, lung squamous cell carcinoma, clear cell renal carcinoma, and lung adenocarcinoma." (PMID 40664642, 2025). "Further, CRISPR-mediated depletion of MECOM attenuated growth potential and stemness in lung squamous cell carcinoma." (PMID 40664642, 2025). "In addition, downregulation of MECOM and PRDM16 expression was also found in LUAD and lung squamous cell carcinomas (LUSC) in the TIMER database (all p < 0.05)." (PMID 35174083, 2022).
Myelodysplasia (2 papers, 2021 to 2023). Clonal hematopoietic stem cell disorders characterized by dysplasia (ineffective production) in one or more hematopoietic cell lineages, leading to anemia and cytopenia. "An alternative to detect specific abnormalities (RUNX1::RUNX1T1, CBFB::MYH11, KMT2A (MLL) and MECOM (EVI1) gene fusions or myelodysplasia-related chromosome abnormalities) is fluorescence in situ hybridization." (PMID 36900154, 2023).
pancreatitis (2 papers, 2020 to 2021). Inflammation of the pancreas. "At day 11, CD3 positive area in MECOM KO mice remained at a level comparable to the acute phase of pancreatitis (day 4), whereas in the control mice it was significantly decreased." (PMID 33762742, 2021).
preeclampsia (2 papers, 2020 to 2024). Preeclampsia is a hypertensive disorder of pregnancy that is characterized by new-onset hypertension with proteinuria presenting after 20 weeks of gestation, and depending on mild or severe forms may initially present with severe headache, visual disturbances, and hyperreflexia. "We found that the four preeclampsia associated variants at MECOM, FGF5, ZNF831, and SH2B3 are among the variants with the highest effect on all three BP traits, particularly on diastolic BP." (PMID 33239696, 2020). "We thus conclude that in addition to the variants near ZNF831 and FTO that exhibited genome-wide significance, BP variants at FGF5, SH3B2, and MECOM also associate with preeclampsia." (PMID 33239696, 2020). "Further analysis of BP variants establishes that variants at MECOM/3q26, FGF5/4q21 and SH2B3/12q24 also associate with preeclampsia through the maternal genome." (PMID 33239696, 2020).
psoriasis (2 papers, 2013 to 2025). An autoimmune condition characterized by red, well-delineated plaques with silvery scales that are usually on the extensor surfaces and scalp. "MECOM’s altered expression in psoriasis was previously shown to correlate with excessive keratinocyte proliferation." (PMID 40650108, 2025). "Many DEG-coded proteins (CCNA2, FYN, PIK3R1, CTGF, F3) and transcription factors (AR, TFDP1, MEF2A, MECOM) were identified as central nodes, suggesting their potential role in psoriasis pathogenesis." (PMID 24303025, 2013). "Abnormal expressions of proteins like MECOM and PRDM2 further indicate their significance in immune modulation and stem cell functions, likely to influence the pathogenesis of psoriasis." (PMID 40650108, 2025). "CCNA2, TFDP1 and MECOM might play role in the hyperproliferation of keratinocytes, whereas FYN may be involved in the disturbed immunity in psoriasis." (PMID 24303025, 2013).
bladder cancer (1 paper, 2023). "This strategy identified a large module of Luminal TFs, including known Luminal-associated TFs (e.g., FOXA1/GATA3/PPARG), as well as TFs with yet unexplored roles in Luminal bladder cancer biology (e.g., HES1, FOXQ1, ZBTB7C, MECOM, GRHL2/3, and TBX3)." (PMID 36944729, 2023).
bone marrow failure (1 paper, 2023). "We have followed up on the human genetic observation that MECOM haploinsufficiency results in early-onset bone marrow failure and by modeling this disorder in primary HSPCs, we show that the functional loss of HSCs is accompanied by alterations in a network of genes critical for HSC maintenance." (PMID 36522544, 2023).
cancers of the cervix (1 paper, 2017). "HPV-driven cancers of the cervix, head and neck, and penis share copy number alteration sites, most notably copy number gains in 3q, which in addition to PIK3CA contains the telomerase RNA component (TERC), MDS1 and EVI1 complex locus (MECOM), SRY-box 2 (SOX2), and TP63 genes." (PMID 28771191, 2017).
chronic pancreatitis (1 paper, 2021). A chronic inflammatory process causing damage and fibrosis of the pancreatic parenchyma. "During mouse embryonic development, pre-acinar cells also transiently expressed MECOM and in the adult mouse pancreas, MECOM was re-expressed when mice were subjected to acute and chronic pancreatitis, conditions in which acinar cells dedifferentiate." (PMID 33762742, 2021). "MECOM mRNA appeared at low levels in the acinar compartment of the normal human pancreas (0.24 ± 0.09 mRNA dots/cell; N = 3) but increased in samples of chronic pancreatitis (1.46 ± 0.10 mRNA dots/cell; N = 3; *p = 0.02)." (PMID 33762742, 2021).
Cirrhosis (1 paper, 2024). A chronic disorder of the liver in which liver tissue becomes scarred and is partially replaced by regenerative nodules and fibrotic tissue resulting in loss of liver function. "MECOM was significantly downregulated in cirrhosis groups and the expression is lowest in advanced decompensation group while highest in control group." (PMID 38369527, 2024).
colorectal adenoma (1 paper, 2023). An adenoma that arises from the colon or rectum. "Consistent with earlier findings, we found that MECOM was upregulated in colorectal adenomas and primary CRCs." (PMID 36609474, 2023).
kidney tumors (1 paper, 2022). "The results of Oncomine revealed that both MECOM and PRDM16 expression were downregulated in lung, breast, gastric, sarcoma, and kidney tumors compared with normal tissues (all p < 0.05)." (PMID 35174083, 2022).
liposarcoma (1 paper, 2018). A usually painless malignant tumor that arises from adipose tissue. "In our study we also noted deleterious mutations in 7 other genes (CTNNB1 (R151H), MECOM (R208C), ZNF536 (T688M), EML4 (W729L), CSMD3 (P627S), PBRM1 (N639K), PPP1R3A (C788Y)) that have also not been described previously in WD/DD liposarcoma." (PMID 29731991, 2018).
lung carcinoma (1 paper, 2022). "In PhenoScanner, 6 out of 12 hub genes (IRAK2, MECOM, ASB4, CDC42BPA, DPF3 and TMEM67) have revealed an association with lung related traits and lung cancer." (PMID 36194576, 2022). "Interestingly, pathways enriched by MECOM and IRAK2 were involved in lung cancer development." (PMID 36194576, 2022).
metastatic tumors (1 paper, 2017). "Chromosomal gains at MECOM and HHLA1 loci suggest that the observed cells were cancer cells and reflect pathophysiological decisive chromosomal aberrations of the primary and metastatic tumors." (PMID 29290959, 2017).
myelofibrosis (1 paper, 2017). A partial or complete replacement of the bone marrow stroma by fibrous tissue. "Only the risk allele of MECOM rs2201862_T was found to have protective effect on myelofibrosis transformation." (PMID 29100304, 2017). "MPN patients harbored the risk allele of MECOM rs2201862T were found to have significantly less myelofibrosis transformation (T vs C: 42.9% vs 57.1%, P = 0.032)." (PMID 29100304, 2017).
neutropenia (1 paper, 2024). A decrease in the number of neutrophils found in the blood. "Additional MECOM fusions have been reported in pediatric patients, including MECOM-RPN1 in a patient with AML with megakaryocytic differentiation and EIF4A2-MECOM in a patient with severe congenital neutropenia and secondary AML." (PMID 38473358, 2024).
ovarian serous carcinoma (1 paper, 2021). "As an example, MECOM expression has shown to be associated with therapeutic resistance in ovarian serous carcinoma." (PMID 34729947, 2021).
polycythemia vera (1 paper, 2017). "Furthermore, the risk alleles of MECOM rs2201862 and HBS1L-MYB rs9376092 were demonstrated to be negatively associated with the risk of developing polycythemia vera." (PMID 29100304, 2017).
primary immunodeficiency (1 paper, 2025). "Given the epigenetic control over primary immunodeficiency and TNF/MAPK signaling pathway regulation, ChIP-qPCR was used to detect histone marker enrichment in CXCL10 and MECOM genes." (PMID 40805064, 2025).
prostate carcinoma (1 paper, 2021). A carcinoma that arises from epithelial cells of the prostate gland. "Interestingly, other oncogenic factors not previously implicated in prostate cancer also exhibited 5′-UTR mutations including MECOM and MLF1." (PMID 34244513, 2021).
pulmonary diseases (1 paper, 2022). "Interestingly, IRAK2 and MECOM hub genes from these COPD network clusters are known for their involvement in different pulmonary diseases." (PMID 36194576, 2022).
squamous cell carcinoma (1 paper, 2021). A carcinoma arising from squamous epithelial cells. "The two remaining cancer associated genes amplified from 3q26—MECOM, encoding for the transcription factor EVI1, and TERC, encoding for the human telomerase RNA component—are not correspondingly overexpressed at the mRNA level in 3q26-amplified squamous cell cancers." (PMID 34436017, 2021).
squamous cervical cancers (1 paper, 2021). "SOX2 and PRKCI display lower levels of mRNA over-expression in 3q26-amplified squamous cervical cancers, while MECOM and TERC show no over-expression." (PMID 34436017, 2021).
uterine carcinosarcoma (1 paper, 2025). A usually aggressive malignant neoplasm arising from the uterine corpus and less often the cervix. "An analysis of TGCA data determined that high MECOM expression in uterine carcinosarcoma was associated with shorter disease-free survival than low MECOM expression." (PMID 41340866, 2025).
uterine corpus endometrial carcinoma (1 paper, 2024). A endometrial carcinoma (disease) that involves the body of uterus. "This study aims to investigate the PRDM gene family, particularly the role of MECOM (MDS1 and EVI1 Complex Locus Protein), in uterine corpus endometrial carcinoma and its underlying molecular mechanisms." (PMID 39468462, 2024).
cancer (49 papers, 2012 to 2026). A tumor composed of atypical neoplastic, often pleomorphic cells that invade other tissues. "A key mechanism underlying these anti-cancer effects was JIB-04’s epigenetic modulation of MECOM via altering H3K27me3 deposition at its promoter." (PMID 40664642, 2025). "MECOM has been previously linked with cancer stem cell properties, malignant transformation, cell proliferation and inhibition of apoptosis through the AKT/mTOR pathway." (PMID 39920655, 2025). "MECOM were associated with regulation of transcription, pathways in cancers and FoxO signaling pathway." (PMID 36194576, 2022). "In the same study, the authors also observed intratumor heterogeneity (an important cancer hallmark) of MECOM mutations in four of 16 analyzed cases (25%)." (PMID 32290321, 2020). "PRDM3/MECOM was recurrently mutated in various cancer types, also reaching a value of 20.1% of mutated samples in SKCM." (PMID 30347759, 2018). "In this review, we will use aberrant regulation of MECOM by ectopic enhancers in AML with chromosome 3q26 rearrangements as a paradigm to discuss mechanisms of aberrant gene control in cancer." (PMID 39853740, 2026). "Noticing MECOM transcript regulation by JIB-04 in cancer cells as well in tumors, we were intrigued to investigate JIB-04 mediated epigenetic regulation of MECOM by modulating histone modifications." (PMID 40664642, 2025). "Our analysis identified numerous SIR-associated mutations in oncogenes (e.g., MECOM, NFATC2) and tumor suppressor genes (e.g., LRP1B, PTPRD), as well as in cancer-associated lncRNAs (e.g., MALAT1, NEAT1)." (PMID 41153425, 2025). "PKNX1, a transcription factor within the MECOM gene family, is another understudied motif with potential roles in neural development, hematopoiesis, and cancer." (PMID 40536817, 2025). "Due to their critical roles in cancer, MECOM and PRDM family members are considered potential therapeutic targets." (PMID 39468462, 2024). "Although MECOM has been widely studied for its oncogenic roles in various cancers, its functional contribution to colorectal tumorigenesis is still not fully understood." (PMID 36609474, 2023). "The dedifferentiated acinar cell fraction showed a signature reminiscent of the acinar cell identity and specifically expressed MECOM, a transcription factor that featured in the pathway “Pathways of cancer”." (PMID 33762742, 2021). "The NGS analyses identified mutations in eight cancer associated genes: ESR1, MECOM, JAK3, KMT2C, CTNNB1, CALR, NCOR1 and AMER." (PMID 34209696, 2021). "We provide insights that in dedifferentiated acinar cells, cancer pathways are upregulated in which MECOM is a critical regulator that suppresses acinar cell death by permitting cellular dedifferentiation." (PMID 33762742, 2021). "A similar observation was made for deep CNAs in ERGs, namely BOP1 (four cancers), ATAD2 (four cancers), MECOM (three cancers), and PHF20L1 (three cancers)." (PMID 32963031, 2020). "Heterogeneity in the mutation frequencies was observed in the different tumor types with higher mutation rates found for PRDM3/MECOM, PRDM8, PRDM9, PRDM15, ZFPM1/FOG1 and ZFPM2/FOG2 in specific cancers." (PMID 30347759, 2018). "Overall, PRDM2, PRDM3/MECOM, PRDM9, PRDM16 and ZFPM2/FOG2 were the most mutated genes with pan-cancer frequencies of protein-affecting mutations higher than 1%." (PMID 30347759, 2018). "PRDM3/MECOM was found to be significantly overexpressed in breast (p < 0.001), ovary (p < 0.001), and colon (p < 0.05) cancer specimens." (PMID 30347759, 2018). "In addition, we also detected multiple PUD risk, cancer-related genes (for example, IHH, GNAS, NHEJ1, JUP and MECOM), which provided potential targets contributing to the different outcomes of PUD or GC." (PMID 38036781, 2023).